TPM1 (tropomyosin 1)
Diseases named in the same sentence as TPM1 in open-access papers (continued):
Sharing a sentence is not in itself a finding about the gene and the disease.
leukoplakia (2 papers, 2017 to 2021). A white patch or plaque on a mucous membrane that cannot be characterized clinically or pathologically as any other disease. "However, the regulation and mechanism of TPM1 in oral leukoplakia is still unknown." (PMID 28182650, 2017). "Leukoplakia is a precancerous lesion in OSCC, and it was found that miR-21 secreted from OSCC cells was correlated with low expression of its target genes, TPM1 and PTEN, and was highly expressed in progressive leukoplakia and OSCC to promote disease progression." (PMID 33718365, 2021).
lymph node metastasis (2 papers, 2017 to 2022). "In our research, TPM1 expression was negatively related with certain clinical parameters, such as disease stage and lymph node metastasis, but positively related to prognosis." (PMID 28182650, 2017). "It was also found that OSCC patients who suffered from disease stageI-II were more likely to have an up-regulated TPM1 expression level, and OSCC patients with lymph node metastasis had a higher probability of exhibiting reduced TPM1 expression." (PMID 28182650, 2017). "The correlations between TPM1 expression level and sex, histological grade, recurrence, disease stage, tumor class, lymph node metastasis and distant metastasis were analyzed." (PMID 28182650, 2017). "Moreover, it was also revealed that lymph node metastasis was remarkably correlative with TPM1 expression level (p<0.01)." (PMID 28182650, 2017). "We found that TPM1 mRNA expression was significantly related with age (p=0.045), gender (p=0.03), pathological stage (p=0.01) and lymph node metastasis (p=0.018), but not others." (PMID 35965538, 2022).
melanoma (2 papers, 2018 to 2021). A malignant, usually aggressive tumor composed of atypical, neoplastic melanocytes. "TPM1 and CXCL12 were alternatively spliced in the melanoma vs. nevus comparison." (PMID 34281234, 2021).
neuroblastoma (2 papers, 2003 to 2018). Neuroblastoma (NB) is the most common solid, extracranial childhood tumor. "Using this approach, Gunning and co-workers revealed the presence of Tpm1.10, Tpm1.11, Tpm1.12, and Tpm4.2 in neuroblastoma cells." (PMID 29191834, 2018).
oral squamous cell carcinoma (2 papers, 2017 to 2025). "Besides, the expression of TPM1 may be related to the aggressiveness of the tumour and the regulation of the immune microenvironment, which may affect the immune surveillance of human oral squamous cell carcinoma." (PMID 40045162, 2025).
senile osteoporosis (2 papers, 2024 to 2025). "Therefore, YO-EVs and the delivered TPM1 hold potential as therapeutic targets for senile osteoporosis." (PMID 38664789, 2024). "Osteocyte-derived extracellular vesicles (YO-EVs) enriched with tropomyosin-1 (TPM1) enhance matrix stiffness and osteogenesis, highlighting their therapeutic potential for senile osteoporosis." (PMID 40564162, 2025).
Stroke (2 papers, 2025). Sudden impairment of blood flow to a part of the brain due to occlusion or rupture of an artery to the brain. "We evaluated the diagnostic potential of FINC and PMGE for atherothrombotic stroke, and of TPM1 for cardioembolic stroke." (PMID 40943257, 2025). "Furthermore, a significant correlation was observed between TPM1 peptide 846 and baseline NIHSS scores (r ~ 0.8), indicating that higher levels of TPM1 are associated with worse clinical status in cardioembolic patients at the onset of stroke." (PMID 40943257, 2025). "Nine days post-stroke, proteins annotated as thin filaments were upregulated, including Ablim1, Dbnl, Parvb, Capg, and Pdlim3; Actn2, Pdlim7, Tpm1, and cofilin 2 (Cfl2) were downregulated." (PMID 41226396, 2025). "In summary, these findings suggest that the biomarkers FINC, PMGE, and TPM1 hold prognostic potential in stroke patients, particularly for differentiating between cardioembolic and atherothrombotic origins and predicting patient outcomes." (PMID 40943257, 2025). "Our proteomic study and statistical analysis identified three proteins, TPM1, FINC, and PMGE, which differ significantly between cardioembolic and atherothrombotic stroke groups." (PMID 40943257, 2025). "In summary, this work presents the discovery of a biomarker panel of three proteins, TPM1, FINC, and PMGE, which differentiate cardioembolic from atherothrombotic stroke." (PMID 40943257, 2025). "TPM1, FINC, and PMGE peptide quantification could aid in differentiating stroke etiology, potentially contributing to more personalized treatment approaches." (PMID 40943257, 2025). "This is the first time TPM1 has been identified as a potential biomarker for the cardioembolic stroke subtype, while FINC and PMGE have been proposed as potential biomarkers for atherothrombotic stroke." (PMID 40943257, 2025). "Similarly, for atherothrombotic stroke, positive results for FINC and PMGE with a negative TPM1 result also achieved 100% specificity and predictive value." (PMID 40943257, 2025).
urothelial carcinoma (2 papers, 2019 to 2025). A malignant neoplasm derived from the transitional epithelium of the urinary tract (urinary bladder, ureter, urethra, or renal pelvis). "For example, decreased TPM1 expression is seen more often in high-grade urothelial carcinoma, MIBC and metastatic bladder cancer than in low-grade urothelial carcinoma, NMIBC and non-metastatic bladder cancer." (PMID 30836651, 2019). "Moreover, BC tissues with negative urine cytology for high-grade urothelial carcinoma (HGUC), absence of nodal metastasis, and lower stage and grade expressed higher TPM1 levels compared with tumors exhibiting positive HGUC cytology, nodal metastasis, higher grade, and advanced stage." (PMID 41231336, 2025).
acute rheumatic fever (1 paper, 2020). "TPM1 encodes the tropomyosin α-1 chain, whereas anti-tropomyosin antibodies have been described in several rheumatic diseases such as Behçet's disease and acute rheumatic fever." (PMID 33301475, 2020).
age (1 paper, 2022). A temporal measurement of the time period elapsed since an identifiable point in the life cycle of an organism. "Our findings suggest that TPM1 might potentially play a similar role in age‐related neurodegenerative diseases as in normal brain aging." (PMID 35148456, 2022).
ascending aortic dilatation (1 paper, 2022). "One (1.9%) developed asymmetric hypertrophy (HCM), mild mitral valve prolapse (MVP) and mild ascending aortic dilatation; additional genetic tests identified a variant of unknown significance in TPM1 and KCNQ1 genes." (PMID 35757141, 2022).
atrial septal defect (1 paper, 2025). Interauricular communication is a congenital malformation characterized by a communication between the atrial chambers of the heart. "In this study, a potentially deleterious TPM1 variant was identified in a family with atrial septal defects (ASD)." (PMID 40438121, 2025).
bladder tumor (1 paper, 2023). "qRT-PCR demonstrated that the mRNA expression levels of ACTA2, FLNA, TAGLN, and TPM1 in bladder tumor cells were significantly decreased compared with normal bladder cells, which corresponded to the results of our prior bioinformatic investigation using public datasets." (PMID 37274283, 2023). "In addition, qRT-PCR and Western blotting demonstrated that the transcription and translation levels of ACTA2, FLNA, TAGLN, and TPM1 were much lower in bladder tumor cells than in normal bladder cells." (PMID 37274283, 2023).
bone tumors (1 paper, 2022). "miR-21: significantly overexpressed in different tumor types, in particular in bone tumors, it is involved in the regulation of many tumor suppressor genes and apoptosis-related proteins including tropomyosin-1 (TPM1), programmed death protein 4 (PDCD4), and metalloproteinase inhibitor 3 (TIMP3)." (PMID 35216464, 2022).
cardioembolic stroke (1 paper, 2025). "Our study reveals that TPM1 exhibits a sensitivity of 40.7% and a specificity of 85.2% for diagnosing cardioembolic stroke." (PMID 40943257, 2025). "TPM1 is involved in abnormal contractions of cardiac muscle, and may contribute to cardioembolic stroke, highlighting its potential as a biomarker for muscle damage, similar to troponin C in diagnosing cardiac injury in ischemic stroke." (PMID 40943257, 2025). "Finally, in the case of TPM1, we found a correlation between its levels and baseline NIHSS scores, indicating that TPM1 may serve as a marker of neurological deficit, particularly in cases of cardioembolic stroke." (PMID 40943257, 2025). "For cardioembolic stroke, a positive TPM1 result along with negative FINC and PMGE results yielded 100% specificity and predictive value." (PMID 40943257, 2025).
cervical (1 paper, 2022). "Furthermore, microRNA‐21 affects other direct target molecules including PDCD-4, TPM-1, FASL, and BTG-2 in order to stimulate its cervical carcinogenesis effect." (PMID 35895593, 2022).
channelopathy (1 paper, 2023). Channelopathies are a group of diseases caused by the dysfunction of ion channel subunits or their interacting proteins. "One such disease is myotonic dystrophy type I (MD1), known as Steinert disease, associated with a DMPK gene defect and channelopathy caused by mutations in genes associated with cardiac function (i.e., TNNT, TNNT2, TTN, TPM1, SYNE1, MTMR1, NEBL, and TPM1), including CACNA1A and CACNA1H." (PMID 37958665, 2023).
cholangiocarcinoma (1 paper, 2021). A carcinoma that arises from the intrahepatic biliary tree (intrahepatic cholangiocarcinoma) or from the junction, or adjacent to the junction, of the right and left hepatic ducts (hilar cholangiocarcinoma). "TPM1 exhibits low levels of expression and has been reported to suppress cell proliferation and migration in addition to inducing the apoptosis of intrahepatic cholangiocarcinoma cells." (PMID 33653339, 2021).
Cirrhosis (1 paper, 2021). A chronic disorder of the liver in which liver tissue becomes scarred and is partially replaced by regenerative nodules and fibrotic tissue resulting in loss of liver function. "TPM1 expression has been previously found in activated HSC colocalizing with αSMA in liver tissue samples from rat livers, and has also been detected in serum and liver tissue from patients, where it has been proposed as potential biomarker of cirrhosis." (PMID 34072510, 2021).
clubfoot (1 paper, 2024). The most common congenital deformation of the foot, occurring in 1 of 1,000 live births. "Initially, genes associatedwith clubfoot (PITX1, TBX4, HOXA9, HOXD10, HOXD12,HOXD13, HOXA9, TPM1, TPM2, COL9A1, FLNB, CASP8,CASP10, UTX, CHD1, RIPPLY2, CAND2, WNT7) werescreened for potential variants." (PMID 38952703, 2024).
Cognitive impairment (1 paper, 2022). Abnormal cognition is characterized by deficits in thinking, reasoning, or remembering. "Besides, Tpm1 has a potential association with cognitive impairments as it was reported as a potential biomarker of AD for its upregulation in the platelets of AD and MCI patients." (PMID 36203804, 2022).
COVID-19 (1 paper, 2023). A disease caused by infection with severe acute respiratory syndrome coronavirus 2. "The cardiac conduction related proteins BIN1 and TPM1 are downregulated in the cardiomyocytes of COVID-19 hearts compared with the control samples, suggesting the virus infection could cause a serious impact on the systolic and diastolic functions of heart." (PMID 38087340, 2023).
CREST syndrome (1 paper, 2023). "The “Tpm1-CM” subpopulation is enriched with transcripts associated with mitochondrial translational termination and elongation, and with different metabolic disorders such as tyrosinemia, Reye syndrome, hypermethioninemia, CREST syndrome, and carnitine palmitoyltransferase II deficiency." (PMID 38110334, 2023).
diabetes (1 paper, 2016). "The high variance impairs statistical confidence that the lower expression of HMW isoforms from TPM1 and TPM4 is associated with diabetes." (PMID 27649540, 2016). "In diabetes, expression of HMW isoforms from TPM1 were markedly decreased (0.55 v 1.00; p = 0.019) but HMW isoforms from TPM4 were not significantly different (0.76 v 1.00; p = 0.205)." (PMID 27649540, 2016). "Expression of LMW isoforms from these genes was not different in diabetes (TPM1: 1.00 v 0.94, p = 0.66; TPM4: 1.00 v 0.81, p = 0.14)." (PMID 27649540, 2016).
Ebstein anomaly (1 paper, 2017). Ebstein's malformation is a rare congenital cardiac anomaly characterized by rotational displacement of the septal and inferior leaflets of the tricuspid valve such that they are hinged within the right ventricle, rather than as expected at the atrioventricular junction. "TPM1 has recently been associated with CHDs in a two year old female with Ebstein anomaly, left ventricular non-compaction, pulmonary hypertension and end-stage heart failure." (PMID 28359939, 2017).
glaucoma (1 paper, 2017). Increased pressure in the eyeball due to obstruction of the outflow of aqueous humor. "Further, Tpm1/2 may regulate other eye diseases such as pterygium and glaucoma and wound healing processes related to EMT." (PMID 27976512, 2017).
Kaposi's sarcoma (1 paper, 2015). A malignant neoplasm characterized by a vascular proliferation which usually contains blunt endothelial cells. "Here we report that KSHV, the causative agent of Kaposi's sarcoma, uses microRNAs to down-regulate the HMW-forms of TPM1." (PMID 26263384, 2015).
leiomyosarcoma (1 paper, 2013). An uncommon, aggressive malignant smooth muscle neoplasm, usually occurring in post-menopausal women. "Finally, we confirmed the expected overexpression of some genes: KIT and ANO1/DOG1 in GISTs, MDM2 and CDK4 in non-myxoid/round cells liposarcomas, CALD1 and tropomyosin genes (TPM1, TPM2) in leiomyosarcomas, PDGFB in DFSPs, MUC1/EMA in synovial sarcomas, and CD34 in SFTs." (PMID 23734203, 2013).
liver fibrosis (1 paper, 2025). "Our study directly confirms that TPM1 is associated with LF and is upregulated in liver fibrosis samples from both humans and mice, providing a stronger theoretical basis for studying TPM1 and LF." (PMID 40943308, 2025).
lung disease (1 paper, 2019). "Thus, NSCLC cells respond to TGFβ-stimulation with upregulation of several cancer type unspecific (VIM, MYLK, MYL9, TPM1) but also more lung disease specific (MYH15) proteins." (PMID 31113982, 2019).
lung tumors (1 paper, 2018). "Furthermore, expression levels of the downstream markers of the corresponding microRNAs, namely PTEN, MARCKs, TPM-1, PDCD4, SPRY-2, ETS-1, ZEB-2, FGFRL-1, EFNA-3, and k-RAS were downregulated in the lung tumor lesions of patients with the underlying condition compared to non-COPD patients." (PMID 29371906, 2018). "However, expression levels of downstream markers TPM-1, TOM-1, CRK, fibulin-2, MIF, and EFNA-3 were greater in the lung tumors than in non-tumor specimens only in patients without COPD." (PMID 29371906, 2018).
Lymphatic Metastasis (1 paper, 2017). Transfer of a neoplasm from its primary site to lymph nodes or to distant parts of the body by way of the lymphatic system. "The occurrence rates of lymphatic metastasis in patients who exhibited a low TPM1 level were higher than in patients with a high TPM1 level." (PMID 28182650, 2017). "The probability of exhibiting an up-regulated TPM1 level was low in patients suffering from lymphatic metastasis." (PMID 28182650, 2017).
muscular disease (1 paper, 2024). Myopathy is a peripheral nervous system disease consisting of any abnormal condition or disease of the muscular tissues; commonly designates a disorder involving skeletal muscle. "TPM1 and PDLIM7 are two genes with important roles in muscle development and muscular diseases." (PMID 37705195, 2024).
Noonan syndrome (1 paper, 2021). Noonan Syndrome (NS) is characterized by short stature, typical facial dysmorphism and congenital heart defects. "RAF1 (Noonan syndrome), SCO2 (Cytochrome c oxidase assembly protein), TNNT2 (Cardiac troponin T), and TPM1 (Tropomyosin-1)." (PMID 34943991, 2021).
periodontal disease (1 paper, 2024). "Our analysis revealed a co-expression network comprising 216 genes, including prominent hub genes such as IL17RC, CCN2, BMP7, TPM1, and TIMP1, which are implicated in periodontal disease." (PMID 39659491, 2024). "Among the top five hub genes highlighted in this interactome are IL17RC, CCN2, BMP7, TPM1, and TIMP1, all of which have been implicated in periodontal disease in conjunction with peri-implant disease." (PMID 39659491, 2024). "The study identified 216 genes, with top hub genes like IL17RC, CCN2, BMP7, TPM1, and TIMP1 involved in periodontal disease." (PMID 39659491, 2024).
peripartum cardiomyopathy (1 paper, 2023). Peripartum cardiomyopathy (PPCM) is an idiopathic, potentially fatal form of dilated cardiomyopathy that develops during the final month of pregnancy or within five months after delivery. "Mutations in Tpm1 have been associated with both HCM, DCM, and with peripartum cardiomyopathy (PPCM)." (PMID 38110334, 2023).
restrictive cardiomyopathy (1 paper, 2025). A type of heart disorder referring to the inability of the ventricles to fill with blood because the myocardium (heart muscle) stiffens and looses its flexibility. "Clinico-molecular characteristics of TPM1 mutations in restrictive cardiomyopathy (RCM)." (PMID 41568329, 2025).
retinal diseases (1 paper, 2022). "It will be interesting to investigate the role of TPM1 in regulating inflammation in these retinal diseases and AD in the future." (PMID 36241997, 2022).
schistosomiasis (1 paper, 2022). An infectious disease caused by parasitic trematodes of the genus Schistosoma that colonize human blood vessels and release eggs that can cause granulomatous reactions leading to acute (swimmer's itch or acute schistosomiasis syndrome) or chronic disease. "Therefore, mutations in TPM1 at 15q22.2 might play a potential role in developing schistosomiasis liver injury." (PMID 35493725, 2022).
Sepsis (1 paper, 2019). Sepsis is defined as life-threatening organ dysfunction caused by a dysregulated host response to infection. "Tpm1, Tpm2, and Tpm3 mRNA levels decreased in the TA after 24 and 48 h of sepsis." (PMID 31660704, 2019). "Tpm1, Tpm2, and Tpm3 mRNA levels decreased in the DIA after 48 h of sepsis." (PMID 31660704, 2019).
squamous cell carcinoma (1 paper, 2016). A carcinoma arising from squamous epithelial cells. "Over-expression of the TPM1 isoform can suppress tumor growth, such as squamous cell carcinoma proliferation in the esophagus." (PMID 27046189, 2016).
systolic heart failure (1 paper, 2018). Heart failure caused by abnormal myocardial contraction during systole leading to defective cardiac emptying. "Also none of the index patients with the TPM1 p.(Asp175Asn) mutation had significant systolic dysfunction (EF<46%) and only one (5%) had a history of systolic heart failure." (PMID 30235249, 2018).
tongue cancer (1 paper, 2017). A malignant neoplasm affecting the tongue. "It was found that, as a potential target of microRNA 21, TPM1 plays a vital role in tongue carcinoma by enhancing apoptosis of cancer cells." (PMID 28182650, 2017). "Our results verified that TPM1 played a vital role in tongue cancer by inducing apoptosis in cancer cells." (PMID 28182650, 2017). "TPM1 expression in tongue cancer has been reported in similar studies." (PMID 28182650, 2017). "Consequently, it is still unknown whether TPM1 functions in the same way in OSCC as it did in tongue carcinoma." (PMID 28182650, 2017). "As an oncogene, microRNA-21 was investigated in solid tumors and observed to be up-regulated in tongue carcinoma, although no luciferase reporter assay results, which could be used to verify the association between miR-21 and TPM1, were presented in any of these studies." (PMID 28182650, 2017).